GSDME (gasdermin E)
Diseases named in the same sentence as GSDME in open-access papers (continued):
Sharing a sentence is not in itself a finding about the gene and the disease.
tumor (continued). "On the other hand, a positive correlation was found between GSDME expression and tumor-related macrophage phagocytosis as well as NK and CD8+T lymphocyte production and function." (PMID 35462927, 2022). "GSDME was recently reported that can prevent tumor growth through enhancing the cell antitumor function." (PMID 35958114, 2022). "Gasdermin E (GSDME) expression is inhibited in many types of cancer, including BC, and tumor GSDME can activate pyroptosis, improving tumor suppression through killer cytotoxic lymphocytes." (PMID 36189269, 2022). "It is shown that the NSCLC patients with lower expression of GSDME in tumor tissues are inclined to have a higher mortality rate after platinum treatment." (PMID 35819638, 2022). "After the As2O3-NPs are internalized by tumor cells, the As2O3 is released into the cytoplasm and GSDME is cleaved following caspase-3 activation." (PMID 35673561, 2022). "GSDME directly induces tumor cell pyroptosis through Caspase-3 and indirectly acts on T lymphocytes through Granzyme B, acting as a tumor suppressor gene." (PMID 35992142, 2022). "After clarifying GSDME function as a tumor suppressor, it is necessary to gain an understanding of how it plays its role in suppressing tumors." (PMID 35462927, 2022). "Consistently, Western blotting analysis of resected tumor tissues revealed increased cleavage of GSDME in GSDME-overexpressing mice after irradiation, while silencing GSDME decreased the cleavage of GSDME." (PMID 36411454, 2022). "We found GSDME expression is high‐regulated in HNSCC tumor tissues (p < .001), and considered it as a poor prognostic biomarker (HR > 1)." (PMID 35574984, 2022). "Evidence suggests that GSDME is a tumor suppressor with reduced expression in many tumors, mainly due to epigenetic silencing caused by methylation of the promoter region." (PMID 35480866, 2022). "First, we examined the expression of GSDME protein in RB patients by IHC assay and found that GSDME protein was significantly reduced in tumor tissue compared with peritumoral normal retinal tissue." (PMID 35480866, 2022). "The combination of oxaliplatin and farnesoid X receptor agonist GW4064 triggered caspase-3/GSDME-driven pyroptosis and slowed tumor growth, thereby enhancing the chemosensitivity of CRC." (PMID 36505474, 2022). "Together, these observations support the notion that GSDMD and GSDME act as tumor suppressors through programmed cell death and immune cell recruitment and propose them as prognostic markers for tumor progression and patient survival." (PMID 35844522, 2022). "Overall, intratumoral injection of CVB3 reduced tumor volume through casp-3/GSDME-mediated pyroptosis." (PMID 36551691, 2022). "Among the members, gasdermin E (GSDME) is unique because its active form requires cleavage by caspase-3, an enzyme involved in tumour cell apoptosis." (PMID 35292781, 2022). "The authors also found that the expression of wild-type DFNA5/GSDME in tumor cells reverses caspase-3 activation, leading to a shift from apoptosis to pyroptosis." (PMID 36091790, 2022). "We collected the connections between these forms of PCD and GSDME-mediated PCD to provide insight into the current understanding of tumor resistance and cancer treatment development." (PMID 34335940, 2021). "Increased cleavage of N-terminal fragment of GSDME was markedly observed in the primary tumor tissues obtained from tetraarsenic hexoxide-administered mice, compared with those from the control mice." (PMID 33558527, 2021). "GSDME is highly expressed in normal cells and is low in tumor cells due to the hypermethylation of GSDME promoter." (PMID 33840390, 2021). "Caspase-3 activation drives GSDME cleavage and pyroptosis, and makes this pathway an attractive target for tumor treatments." (PMID 33868312, 2021). "For example, induced activation of GSDME has beneficial effect in treating various cancers because it promotes a more inflammatory tumor milieu." (PMID 33868312, 2021).
tumor (continued). "Activated GSDMB and GSDME induce the pyroptosis of cancer cells and enhance anti-tumor immunity, thus creating a positive feedback loop of pyroptosis and anti-tumor immunity." (PMID 34931767, 2021). "In tumor cell lines, knockout of the corresponding gene in EMT6 and CT26 cells that express GSDME enhances tumor growth." (PMID 34490126, 2021). "Silencing eEF-2K amplifies GSDME cleavage triggered by doxorubicin, and decreases inappropriate autophagy, which leads to stronger tumor inhibition." (PMID 34335940, 2021). "Decreased expression of a primary mediator of pyroptosis, gasdermin D, is linked to enhanced cancer cell proliferation in vitro and tumor growth in vivo, whereas increased gasdermin E expression enhanced drug sensitivity of tumor cells." (PMID 33572196, 2021). "The expression of GSDME greatly increases the number of TILs (tumor infiltrating lymphocytes) and the phagocytic capacity of macrophages." (PMID 34381721, 2021). "TNM plot analysis showed that the expression of caspase-4 and GSDME was significantly inhibited in clinical tissues in normal, tumor (1097), and metastatic states, which was consistent with the earlier investigation." (PMID 34659633, 2021). "In tumors with low levels of GSDME, activated caspase-3 elicits apoptosis, while if the tumor expresses high levels of GSDME, caspase-3 switches its downstream pathway from apoptosis to pyroptosis or apoptosis and pyroptosis." (PMID 33467668, 2021). "Studies had showed that GSDMD and GSDME-mediated canonical inflammasome signaling and pyroptosis play vital roles in the immune response of cancer tissues through modulating the tumor immune microenvironment." (PMID 34421915, 2021). "Taken together, these results indicate that tetraarsenic hexoxide exerts the anti-tumor effects via GSDME-mediated pyroptosis in aggressive TNBC cells." (PMID 33558527, 2021). "In the case of GSDME, a tumor suppressor which activates pyroptosis, this enhances antitumor immunity." (PMID 34459122, 2021). "Accumulative evidence highlights GSDME as a candidate tumor suppressor and a critical factor influencing treatment responses." (PMID 34901025, 2021). "As such, GSDME expression was shown to increase phagocytosis of tumor cells by macrophages as well as the number and cytolytic activity of tumor-infiltrating natural-killer and CD8+ T lymphocytes, resulting in reduced tumor growth." (PMID 34971436, 2021). "Conversely, in another study using the AOM/DSS model, GSDME-dependent pyroptosis and the subsequent release of HMGB1 are associated with colitis and tumor development." (PMID 35111698, 2021). "GSDME was shown to play the role of a tumor suppressor through the mechanisms of pyroptosis activation and increased anti-tumor immunity." (PMID 34731088, 2021). "In another published paper, GSDME knockout in colorectal mice model showed decreased pyroptosis degree, attenuated tumor size, and number." (PMID 34731088, 2021). "For instance, GSDME was reported to be activated by miltirone, thereby induced pyroptosis and inhibited the tumor growth in HCC." (PMID 34731088, 2021). "Previously, the methylation patterns of the GSDME gene across fourteen distinct tumor types were analyzed through The Cancer Genome Atlas (TCGA) methylation data." (PMID 33634141, 2021). "GSDME also enhances the number and activity of tumour-infiltrating natural-killer (NK) and CD8 + T-lymphocytes, as well as phagocytosis of tumour cells by tumour-associated macrophages." (PMID 33602906, 2021). "More than acting as a tumor suppressor, GSDME functions as a potential therapeutic target in the battle against cancer." (PMID 34335940, 2021). "They demonstrated that administration of chemotherapeutic nanocarriers reactivates expression of GSDME and facilitates GSDME mediated pyroptotic cell death of tumor cells." (PMID 33941231, 2021). "The authors also observed that granzyme B cleavage of GSDME resulted in increased antitumor immunity and reduced tumor growth." (PMID 33840390, 2021).
tumor (continued). "Although GSDME is known as a tumor suppressor, it is reported that GSDME is highly expressed in several normal tissues and chemotherapy toxicity influences GSDME-mediated pyroptosis, eventually leading to the damage of normal cells." (PMID 33558527, 2021). "Overexpression of wild type GSDME inhibits tumor growth in immunocompetent mice, whereas overexpression cancer associated GSDME mutants which lose the ability to execute pyroptosis fail to delay tumor growth." (PMID 33941231, 2021). "Gasdermin E (GSDME) is a potent tumor suppressor and has the potential to evoke anti-tumor immunity through mediating pyroptosis in cancer cells." (PMID 34108030, 2021). "Conversely, lentiviral-mediated expression of full length GSDME decreases the tumor growth of 4T1 and B16 tumor cell lines when grafted into immunocompetent mice." (PMID 34490126, 2021). "The tumor-suppressing role of GSDME-mediated pyroptosis is not only related to direct killing of neoplastic cells, but also to recruitment and activation of immune cells with antitumor functions." (PMID 35111698, 2021). "After administering MCPP to tumor cells and followed by laser irradiation, MCPP induced rapid and durable GSDME‐dependent tumor cell pyroptosis." (PMID 34705343, 2021). "The expression of GSDME, which acts as a tumor suppressor, is frequently silenced in cancer cells, most likely due to promoter methylation." (PMID 33406603, 2021). "In vitro, CCCR-NK92 cells rapidly killed H1299 cells through GSDME-mediated pyroptosis and, in vivo, significantly inhibited tumor growth." (PMID 34429144, 2021). "For instance, GSDME has been reported to function as a tumor suppressor gene by directly inducing tumor cell pyroptosis through caspase 3, as well as indirectly by acting on T lymphocytes through Granzyme B14,47." (PMID 33589596, 2021). "In this study, we demonstrate that in addition to promoter methylation, epithelial-mesenchymal transition (EMT) dictates GSDME gene expression in diverse tumor models." (PMID 34901025, 2021). "Induction of GSDME-mediated pyroptosis evokes anti-tumor immunity, which enhances the ability of cisplatin to regress non-small cell lung cancer." (PMID 33941231, 2021). "By using decitabine to demethylate GSDME in combination with nanoliposomes carrying chemotherapy drugs that activate caspase-3, the group effectively reversed GSDME silencing in tumor cells and induced pyroptosis." (PMID 34429144, 2021). "In summary, GSDME-dependent pyroptosis was revealed in CAP treated tumor cells, and mechanism study illustrated that the apoptotic pathway, ROS/Caspase-9/Caspase-3/GSDME, was activated in GSDME high-expressed tumor cells to initiate pyroptosis." (PMID 32341339, 2020). "Among them, besides GSDMD, GSDME has been the most widely used in the study of pyroptosis of tumor cells in recent years." (PMID 33133646, 2020). "All these results provided evidence that cleavage of GSDME at D270 to disturb cell membranes via pore formation was required for tumour suppression." (PMID 32404864, 2020). "It is noted that cancer cells develop epigenetic suppression of GSDME expression and LOF mutations to avoid GSDME-mediated tumor suppression." (PMID 32516941, 2020). "It has been demonstrated that treatment of GSDMEwt mice with iron dextran promoted cleavage of GSDME and significantly decreased the tumor growth." (PMID 32340261, 2020). "In our study, GSDME, one of gasdermin family members which are known as a prerequisite for pyroptosis occurrence, was found to be highly expressed in some tumor cells." (PMID 32341339, 2020). "In summary, it can be concluded that GSDME has an important effect on the mechanism of tumor cells death." (PMID 33133646, 2020). "Recently, GSDME has been found to exert a marked effect on the tumor immune microenvironment via pyroptosis." (PMID 33033617, 2020).
tumor (continued). "Cysteinyl aspartate specific proteinase-3 (Caspase-3) is a common key protein in the apoptosis and pyroptosis pathways, and when activated, the expression level of tumor suppressor gene Gasdermin E (GSDME) determines the mechanism of tumor cell death." (PMID 33133646, 2020). "GSDME-mediated pyroptosis is correlated with the side effects of chemotherapy and anti-tumor immunity." (PMID 33133646, 2020). "In summary, GSDME-mediated pyroptosis plays an important role in cancer treatment and anti-tumor immunity." (PMID 33133646, 2020). "Collectively, these studies define a new functional intersection between GSDME‐dependent pyroptosis and T‐cell/NK cell responses to tumor cells." (PMID 33033617, 2020). "Mechanistically, granzyme B (GzmB) from killer cytotoxic lymphocytes induces GSDME‐dependent pyroptosis in tumor cells, by both directly cleaving GSDME and indirectly activating caspase‐3 to cleave GSDME." (PMID 33033617, 2020). "In the present study, we first reported that CAP effectively induced pyroptosis in a dose-dependent manner in Gasdermin E (GSDME) high-expressed tumor cell lines." (PMID 32341339, 2020). "Taken together, we revealed that CAP also distinctly induced typical GSDME-mediated pyroptosis in tumor cells." (PMID 32341339, 2020). "When the expression of GSDME is low, it will lead to the classical mechanism of tumor cell death, which is apoptosis." (PMID 33133646, 2020). "The authors provided further evidence that the function of killer lymphocytes (CD8+ T or NK cells) was enhanced in tumours with the overexpression of wild-type GSDME." (PMID 32404864, 2020). "GSDME cleavage at D270 by GzmB/caspase 3 promoted pore formation to induce pyroptosis and suppress tumour growth through the enhancement of anti-tumour adaptive immunity." (PMID 32404864, 2020). "In contrast, iron supplementation was ineffective in the reduction of tumor weight in GSDME-knockdown mice." (PMID 32340261, 2020). "Taken together, these results indicated that caspase-9/caspase-3/GSDME axis contributed to CAP-induced tumor cell pyroptosis." (PMID 32341339, 2020). "In conclusion, our work provides a conceptual advance in understanding the function of GSDME in the apoptotic program and tumor suppression." (PMID 30976076, 2019). "In this study, we have investigated the methylation patterns of the Gasdermin E gene across 14 different tumor types using The Cancer Genome Atlas (TCGA) methylation data (N = 6502)." (PMID 31752152, 2019). "The results showed that the size and weight of the xenograft tumours in the GSDME-knockout group were comparable to those in the WT group." (PMID 30804337, 2019). "In conclusion, these data suggested that GSDME is a tumor suppressor gene, which is often epigenetically inactivated through DNA methylation in different types of cancer." (PMID 31434357, 2019). "The protein expression levels of the pyroptosis-related protein GSDME and DNA methyltransferases (Dnmt1, Dnmt3a, and Dnmt3b) in tumor tissues were evaluated by western blotting to explore the mechanism of the in vivo antitumor activity of As2O3-NPs." (PMID 31637008, 2019). "Lastly, GSDME expression is regulated by p5324, which is known to activate the transcription of numerous tumor suppressors and activators of apoptosis." (PMID 30976076, 2019). "SSZ/ID co-treatment significantly reduced A375 cell-driven tumor growth, accompanied with the increased GSDME cleavage as compared to the control PBS group." (PMID 30287942, 2018). "Many tumor cells evade this pathway by epigenetically silencing GSDME." (PMID 41315764, 2026). "In tumor cells, GSDME can inhibit cell proliferation and activate anti-tumor immunity, indicating that GSDME may function as a tumor suppressor 39-41." (PMID 39816682, 2025). "Evidence suggests that GSDME plays a role in tumor chemoresistance." (PMID 40894196, 2025). "When GSDME was knocked out in cancer cells, tumor growth was enhanced." (PMID 40544161, 2025).
tumor (continued). "Our study as well as previous studies suggest that GSDME is an effective anti-tumour target." (PMID 40756987, 2025). "Notably, GSDME-overexpressing tumors in BALB/c mice exhibited enhanced tumor suppression, characterized by elevated CTLs and cytokine release." (PMID 41291696, 2025). "Notably, granzyme B further contributed to pyroptosis via cleavage of GSDME, creating a feedforward loop that amplified tumor cell death." (PMID 41239499, 2025). "In most solid tumors, GSDME exerts tumor-suppressive effects." (PMID 40568597, 2025). "Furthermore, infiltrated NK cells enhanced GSDME-dependent pyroptosis in tumor cells through granzyme release, establishing a positive feedback loop that amplified anti-tumor immunity." (PMID 41144149, 2025). "Public data analyses suggest that the infiltration levels of CAFs in tumor tissues are positively correlated with GSDMD and GSDME expression in malignant cells, implying that CAFs may mediate pyroptosis in tumor cells through specific molecular crosstalk." (PMID 40755775, 2025). "GSDME is an important member of the Gasdermin family of proteins, capable of converting caspase-3-mediated apoptosis into pyroptosis in cancer cells and activating anti-tumor immunity." (PMID 40538398, 2025). "Research has found that ALKBH4 can transcriptionally suppress GSDME activation by inhibiting H3K4me3 histone modifications at its promoter region, thereby reducing tumor cell sensitivity to 5-FU treatment, findings that highlight the importance of histone modifications in GSDME regulation." (PMID 40568597, 2025). "Mechanistically, enhanced phagocytosis of GSDME-expressing tumor cells by macrophages might contribute to increased lymphocyte infiltration." (PMID 40645933, 2025). "GSDME, a newly identified tumor suppressor, modulates its induced focal death in a phosphorylation-dependent manner, which enhances the anti-tumor immune response." (PMID 41216288, 2025). "In addition, the cleavage of caspase-3-related sites by GzmB can activate the GSDME protein as a tumor suppressor." (PMID 40698137, 2025). "Furthermore, GSDME is abundantly expressed in both normal tissue cells and tumor‐infiltrating macrophages, which can exacerbate the toxicity and side effects associated with chemotherapy." (PMID 40783818, 2025). "Additionally, the measurement of LDH levels in the supernatant, colony formation assays, and cellular imaging counting further validated the critical involvement of GSDME in fosinopril’s dominant anti-tumor effects." (PMID 41271670, 2025). "GSDME demonstrates a context-dependent dual role in tumor biology, exhibiting both tumor-suppressive and oncogenic activities that highlight the functional plasticity of this molecule within complex tumor microenvironment regulatory networks." (PMID 40568597, 2025). "However, GSDME expression in the tumor core was higher compared to the tumor periphery and distant areas." (PMID 40544161, 2025). "Furthermore, as a potential clinical therapeutic agent to treat TNBC, HRP provides a new approach for developing chemotherapy drugs with immunotherapeutic properties for the treatment of tumor cells with low GSDME expression." (PMID 40432601, 2025). "Additionally, SIRPI relieves the hypoxia of tumor based on its excellent catalase‐like (CAT‐like) enzyme activity, enabling efficient ROS generation to trigger specific pyroptotic tumor cell death via the caspase‐3/GSDME pathway in tumor tissue." (PMID 39604790, 2025). "Our results revealed that combination treatment induced GSDME‐mediated pyroptosis in tumor cells." (PMID 40995667, 2025). "Mechanistic studies indicate that GSDME-mediated pyroptosis can promote tumor antigen presentation and enhance T cell infiltration by releasing inflammatory factors such as IL-1β and IL-18, thereby improving the tumor immune microenvironment." (PMID 40568597, 2025).